STAG3L2 (STAG3 cohesin complex component like 2 (pseudogene))
Synonyms: MGC131759; STAG3L2P
Gene: Transcribed unprocessed pseudogene on chromosome 7 (74,882,705 to 74,890,402, reverse strand). Ensembl gene ENSG00000277072.
Subcellular location: Nucleus
Diseases named in the same sentence as STAG3L2 in open-access papers:
STAG3L2 is named in the same sentence as 1 disease in open-access papers, as found by Europe PMC text mining. Sharing a sentence is not in itself a finding about the gene and the disease.
STAG3L2 shares sentences with these, for which no sentence is quoted: ovarian insufficiency (1 paper).